PITPNA (phosphatidylinositol transfer protein alpha)
Description:
Catalyzes the transfer of phosphatidylinositol (PI) and phosphatidylcholine (PC) between membranes. Shows a preference for PI and PC containing shorter saturated or monosaturated acyl chains at the sn-1 and sn-2 positions. Preference order for PC is C16:1 > C16:0 > C18:1 > C18:0 > C20:4 and for PI is C16:1 > C16:0 > C18:1 > C18:0 > C20:4 > C20:3.
Synonyms: PITPN; VIB1A; HEL-S-36; PI-TPalpha
Tractability: Small molecule: a structure with a bound ligand is known; it has a high-quality binding pocket. PROTAC: ubiquitination databases record sites on it; its protein half-life has been measured.
Gene: Protein-coding gene on chromosome 17 (1,517,718 to 1,562,792, reverse strand). Ensembl gene ENSG00000174238.
Subcellular location: Cytoplasm, cytosol; Nucleus
Subcellular location (Human Protein Atlas): Cytosol; Vesicles
Pathways (Reactome):
Developmental Biology: Role of second messengers in netrin-1 signaling
Immune System: Gene and protein expression by JAK-STAT signaling after Interleukin-12 stimulation
Gene Ontology:
Molecular function: lipid binding; phosphatidylcholine binding; phosphatidylcholine transfer activity; phosphatidylcholine transporter activity; phosphatidylinositol binding; phosphatidylinositol transfer activity; protein binding; phosphatidylglycerol binding; quaternary ammonium group binding
Biological process: phospholipid transport; lipid metabolic process; visual perception; axonogenesis; intermembrane lipid transfer; lipid translocation
Cellular component: extracellular exosome; cytoplasm; cytosol; nucleus
Genetic constraint (gnomAD): Loss-of-function variants: 7 observed, 27.33 expected, observed/expected ratio (o/e) 0.26, 90% interval 0.14 to 0.48. The upper end of that interval is the gene's LOEUF score, 0.48, which puts it in group 2 of 6, group 1 being the genes least tolerant of losing a copy. Missense variants: 136 observed, 243.97 expected, observed/expected ratio (o/e) 0.56, 90% interval 0.48 to 0.64. Synonymous variants: 88 observed, 89.34 expected, observed/expected ratio (o/e) 0.99, 90% interval 0.83 to 1.18.
Homologues: Orthologues: dog PITPNA (99% identical), mouse Pitpna (99% identical), rabbit PITPNA (99% identical), guinea pig PITPNA (98% identical), rat Pitpna (90% identical), chimpanzee PITPNA (90% identical), tropical clawed frog pitpna (87% identical), macaque PITPNA (84% identical), pig PITPNA (84% identical), zebrafish pitpnab (79% identical), zebrafish pitpnaa (79% identical), Caenorhabditis elegans Y54F10AR.1 (58% identical). Paralogues in human: PITPNB (77% identical), PITPNM1 (50% identical), PITPNM2 (46% identical), PITPNC1 (41% identical), PITPNM3 (6% identical).
Diseases named in the same sentence as PITPNA in open-access papers:
PITPNA is named in the same sentence as 7 diseases in open-access papers, as found by Europe PMC text mining. Sharing a sentence is not in itself a finding about the gene and the disease. The quoted sentences say what the papers report.
pancreatic cancer (1 paper, 2022). "A necroptosis-relevant risk model was developed for predicting pancreatic cancer survival and responses to immuno- and chemotherapy, comprising MYEOV, HDAC4, TLDC1, PITPNA, FNDC3B, HMGXB4, and BAX." (PMID 35662734, 2022).
cancer (3 papers, 2013 to 2023). A tumor composed of atypical neoplastic, often pleomorphic cells that invade other tissues. "The phosphatidylinositol transfer protein alpha/beta isoform (PITPα/β) has been reported to play an essential role in integrating phosphoinositide trafficking and lipid metabolism in diverse cellular processes but remains unexplored as a potential target for cancer treatment." (PMID 37963877, 2023). "PITPNA has not been previously reported as a cancer biomarker and warrants further investigation." (PMID 25290619, 2014).
PITPNA also shares sentences with these, for which no sentence is quoted: tumor (2 papers); COVID-19 (1); diabetes (1); Miller-Dieker syndrome (1); renal carcinoma (1).